PTPN1 (protein tyrosine phosphatase non-receptor type 1)
Diseases named in the same sentence as PTPN1 in open-access papers (continued):
Sharing a sentence is not in itself a finding about the gene and the disease.
viral infection (6 papers, 2016 to 2024). "As one of the essential members of the PTP superfamily, PTPN1 has various cellular functions, such as regulating the innate immune response, which is closely related to viral infections." (PMID 38783392, 2024). "PTPN1 could be a valuable therapeutic target for drug development against viral infections." (PMID 38783392, 2024). "PTPN1 proteins are evolutionarily conserved across different species and share a conserved region in their catalytic site, and the IFN response is a universal pathway for inhibiting viral infections." (PMID 38783392, 2024).
cognitive decline (5 papers, 2017 to 2023). "Discriminant analysis showed that the best predictors of cognitive decline were EFTUD2, COPZ1, PTPN1, FAXDC2, MLST8 and age." (PMID 29896099, 2018).
Cognitive impairment (5 papers, 2016 to 2024). Abnormal cognition is characterized by deficits in thinking, reasoning, or remembering. "In addition, the combination of PTPN1, COPZ1, FAXDC2, EFTUD2 and MLST8 is a useful signature for cognitive impairment." (PMID 29896099, 2018).
diabetic nephropathy (5 papers, 2009 to 2025). "A careful modular dissection and examination of networks from diabetic nephropathy datasets exhibit the interactions between EGFR with PTPN1 and CAV1 through AKT1 activation." (PMID 19997558, 2009). "On the basis of these observations supported by the literature, we have proposed the interactions of PTPN1 with EGFR and with CAV1 as the new potential interactions in diabetic nephropathy." (PMID 19997558, 2009). "(c) The third network portrays unique interactions PTPN1 with EGFR and CAV1 which could lead to an impaired vascular function in diabetic nephropathy condition." (PMID 19997558, 2009).
leukemia (5 papers, 2010 to 2026). A malignant (clonal) hematologic disorder, involving hematopoietic stem cells and characterized by the presence of primitive or atypical myeloid or lymphoid cells in the bone marrow and the blood. "Exclusion criteria are specific mutations in PTPN1 connected to leukemia and mutations in genes connected to the development of hypertrophic cardiomyopathy (e.g., RIT1)." (PMID 35407641, 2022). "The findings showed that PTPN6, PTPN18, and PTPN22 had higher expression levels in leukemia than in normal blood samples, while PTPN1 had a lower expression level in the former than the latter." (PMID 36699453, 2022).
liver cancer (5 papers, 2019 to 2023). An epithelial or non-epithelial malignant neoplasm that arises from the liver. "Taken together, these results indicated that PTPN1 (PTP1B) is a promising immunotherapy target associated with T cell function for liver cancer." (PMID 36741874, 2023). "Univariate and multivariate Cox regression analysis then revealed PTPN1 as an independent prognostic factor with a high risk of liver cancer." (PMID 36741874, 2023). "Then, we explored the association between the expression of PTPN1 and the clinical characteristics and survival of patients with liver cancer in the TCGA and ICGC databases." (PMID 36741874, 2023). "Overall, these results suggested that the up-regulated expression of PTPN1 was associated with advanced tumor stage and poor prognosis of patients with liver cancer." (PMID 36741874, 2023). "Herein, we define an additional pathway in liver cancer: the cytokine-cytokine receptor interaction closely associated with PTPN1." (PMID 36741874, 2023). "Single-cell RNA-seq analysis further illustrated that the enrichment of PTPN1 in the T cell population may be linked to its exhaustion in the liver cancer microenvironment." (PMID 36741874, 2023). "Thus, it might be speculated that PTPN1 was elevated in liver cancer infiltrating T cells and appeared to be associated with T cell exhaustion." (PMID 36741874, 2023). "Kaplan–Meier analysis showed that the higher expression of PTPN1 was connected to a shorter prognosis time (OS) of liver cancer patients." (PMID 36741874, 2023). "Previous research has shown that PTPN1 increased in liver cancer tissues or liver cancer cell lines, which was consistent with our analysis from public databases." (PMID 36741874, 2023). "Immunohistochemical staining showed that PTPN1 was significantly upregulated in liver cancer tissue compared to normal liver tissue." (PMID 36741874, 2023). "To illustrate the potential biological functions and pathways of PTPN1 in liver cancer, we first screened DEGs between the high-expression group and the low-expression group of PTPN1." (PMID 36741874, 2023). "To further identify the specific molecular mechanism affected by PTPN1 in liver cancer, we also conducted a GSEA pathway analysis using KEGG gene sets." (PMID 36741874, 2023). "In this study, we conducted a comprehensive bioinformatics analysis on PTPN1 (mRNA expression level of PTP1B) in liver cancer based on multiple public databases." (PMID 36741874, 2023). "To further investigate the immune-related role of PTPN1 in liver cancer, we first analyzed the correlation between PTPN1 expression and 47 types of immune checkpoints in the TCGA and ICGC databases." (PMID 36741874, 2023). "Next, we explore the relationship between PTPN1 expression and clinical characteristics of liver cancer." (PMID 36741874, 2023). "Using GEO database, single-cell RNA-seq analysis was then performed to identify the PTPN1-expressed immune infiltration cell in liver cancer." (PMID 36741874, 2023). "Meanwhile, the upregulation of PTPN1 in liver cancer was validated in the ICGC database and the HPA database, respectively." (PMID 36741874, 2023). "Our study showed that the expression of PTPN1 was increased in advanced liver cancer, leading to a worse prognosis for patients." (PMID 36741874, 2023). "We further assessed the protein expression level of PTPN1 in liver cancer using the HPA database." (PMID 36741874, 2023). "Univariate and multivariate Cox regression analysis was then used to confirm whether PTPN1 was an independent prognostic factor of liver cancer." (PMID 36741874, 2023). "Since PTPN1 was considered a potential oncogenic gene related to patients with advanced liver cancer, we also wonder whether PTPN1 has a prognostic significance for liver cancer." (PMID 36741874, 2023). "The increased expression of PTPN1 in liver cancer was confirmed by the ICGC database." (PMID 36741874, 2023). "We found that PTPN1 was overexpressed in various cancers, including liver cancer." (PMID 36741874, 2023).
liver cancer (continued). "Furthermore, up-regulated PTPN1 was connected to advanced tumor stage (p < 0.05) and worse prognosis (p < 0.01) in liver cancer." (PMID 36741874, 2023). "The results indicated the oncogenic role of PTPN1 in the development of liver cancer." (PMID 36741874, 2023). "The results indicated that PTPN1 was independent of clinical features (including age, gender, and stage) and acted as a high-risk factor (hazard ratio > 1) for liver cancer patients in the TCGA database and the ICGC database." (PMID 36741874, 2023). "Overall, PTPN1 (PTP1B) closely related to T cell may function as an immunotherapy target for liver cancer." (PMID 36741874, 2023). "Together, we found strong evidence that PTPN1 may function as an immune regulator that affects the functions of T cells infiltrated in liver cancer." (PMID 36741874, 2023). "Subsequently, we may speculate that the cytokine-cytokine receptor interaction acts as a critical mechanism in PTPN1-regulated immune responses in liver cancer." (PMID 36741874, 2023). "Inspired by the reported role of PTPN1 as an immune checkpoint, gene function and pathway analysis were performed to explore whether PTPN1 was involved in immune response processes in liver cancer." (PMID 36741874, 2023). "Notably, most of the results pointed to T cell-related immune responses and pathways, indicating that the function of T cells might be affected by PTPN1 and its related genes in liver cancer." (PMID 36741874, 2023). "Therefore, PTPN1 may be involved in immune responses of liver cancer, in which the cytokine-cytokine receptor interaction pathway may be the underlying mechanism." (PMID 36741874, 2023). "The results demonstrated that PTPN1 expression was enriched in patients with advanced stage in the TCGA and the ICGC databases, which further illustrated the oncogenic role of PTPN1 in liver cancer." (PMID 36741874, 2023). "The mRNA expression of PTP1B (PTPN1) was increased in patients with most malignancies (all p < 0.05), including liver cancer (p < 0.001)." (PMID 36741874, 2023). "A Chi-square test indicated that PTPN1 and MAP3K11 expression was also higher in HCC tissues than normal liver tissues in human liver cancer tissue microarray(TMA) slides purchased from U.S. Biomax (NO: LV1501) containing 10 normal liver and 120 HCC tissues." (PMID 31527306, 2019). "Overall, our study shed light on the upregulation of PTPN1 with advanced stage and poor prognosis in liver cancer and revealed PTPN1 (PTP1B) as a potential immunotherapy target due to its close association with immune-related pathways, immune checkpoints, and infiltrating T cells." (PMID 36741874, 2023). "The heatmaps showed the immune checkpoints significantly related to PTPN1 (p < 0.001) in the TCGA and ICGC databases, showing the positive correlation between the expression of most immune checkpoints and PTPN1 in liver cancer." (PMID 36741874, 2023).
metastatic tumors (5 papers, 2016 to 2025). "In our study, we have found association of PTPN1 high expression with NB poor outcome, as indicated by PTPN1 enrichment in metastatic disease, and in samples from high stage and intermediate/high-risk NB patients." (PMID 31837707, 2019).
colon adenocarcinoma (4 papers, 2020 to 2026). "To examinewhether PTP1B was linked to ER stress signaling, we analyzed expressioncorrelations between PTPN1 and two central ER stresssensors in primary colon adenocarcinoma samples from TCGA." (PMID 41432362, 2026). "A correlation was observed between the expression of PTPN1 and ETS1 in colon adenocarcinoma samples." (PMID 40356520, 2025).
anaplastic large cell lymphoma (3 papers, 2021 to 2024). Anaplastic large cell lymphoma (ALCL) is a rare and aggressive peripheral T-cell non-Hodgkin lymphoma, belonging to the group of CD30-positive lymphoproliferative disorders, which affects lymph nodes and extranodal sites. "Studies have shown that PTPN1 and PTPN2 deficiency in anaplastic large cell lymphoma (ALCL) leads to ALK-TKI resistance in ALCL." (PMID 36115852, 2022). "Furthermore, loss of PTPN1 and PTPN2 expression was recently identified as an important driver of anaplastic large cell lymphoma (ALCL) resistance to anaplastic lymphoma kinase (ALK) inhibitors." (PMID 38334623, 2024). "In addition, PTPN1 and PTPN2 have been shown to dephosphorylate ALK and PTPN11 in anaplastic large cell lymphomas, and gene deletion of either PTPN1 or PTPN2 induced resistance to ALK inhibitors." (PMID 34957126, 2021).
Autoimmunity (3 papers, 2023 to 2025). The occurrence of an immune reaction against the organism's own cells or tissues. "Most importantly, this was achieved in the absence of the development of cytokine release syndrome or autoimmunity, suggesting that targeting PTPN1 and PTPN2 in vivo may not be associated with overt immune-related toxicities." (PMID 37766318, 2023).
cardiac hypertrophy (3 papers, 2017 to 2022).
cervical cancer (3 papers, 2020 to 2025). A primary or metastatic malignant neoplasm involving the cervix. "Furthermore, SC targeted protein tyrosine phosphatase non-receptor type 1 (PTPN1) and inhibited the activation of the PI3K/AKT signaling pathway, presenting a potential treatment strategy for cervical cancer." (PMID 41339928, 2025).
major depressive disorder (3 papers, 2021 to 2025). An episode of depression lasting two or more weeks without an intervening episode of mania. "For example, the gene nearest the dog-directed aggression locus, PTPN1, is associated in humans with intelligence, cognitive performance, educational attainment, and major depressive disorder." (PMID 41284867, 2025). "For the remaining 6 psychiatric diseases, a positive Wald ratio effect was observed for RHEBL expression and bipolar disorder, and negative Wald ratio effects for SUOX expression and anorexia risk, and for PTPN1 expression and major depressive disorder risk." (PMID 33417599, 2021). "For example, a genome-wide significant locus near PTPN1 (dog-directed aggression) overlapped with human measures of Intelligence, Educational attainment, and major depressive disorder." (PMID 41284867, 2025).
neuroblastoma (3 papers, 2020 to 2024). Neuroblastoma (NB) is the most common solid, extracranial childhood tumor. "Knock-down of PTPN1 in SH-SY5Y cells increased the protein phospho-tyrosine content upon EGF stimulation, as well as cell proliferation, whereas high PTPN1 protein expression in neuroblastoma tumors associated with poor prognosis." (PMID 34957126, 2021). "Potential PTPN1 substrates relevant in neuroblastoma include, among others, RTK, JAK/STAT, SFK, p130Cas, and PERK." (PMID 34957126, 2021). "It will be important to define the direct substrates of PTPN1 in neuroblastoma cells upon different conditions of growth and differentiation." (PMID 34957126, 2021). "PTPN1 has been linked to tyrosine dephosphorylation of the intracellular pool of ALK in mouse fibroblasts, raising the possibility that PTPN1 may dephosphorylate ALK in neuroblastoma cells." (PMID 34957126, 2021). "This suggests a regulatory role for PTPN1 in transformation of neuroblastoma cells." (PMID 34957126, 2021). "The possibility exists that ALK and PTPN11 are direct substrates of PTPN1 and PTPN2 in neuroblastoma cells." (PMID 34957126, 2021).
schizophrenia (3 papers, 2007 to 2026). A major psychotic disorder characterized by abnormalities in the perception or expression of reality. "JUN and two of the miRNA targets (CCND2 and PTPN1) in the network have previously been associated with schizophrenia." (PMID 17849003, 2007). "Interestingly, two of the genes in this network have previously been associated with schizophrenia as deregulated in postmortem brains (CCND2) or positioned under a highly significant linkage peak (PTPN1)." (PMID 17849003, 2007).
chronic lymphocytic leukemia (2 papers, 2020 to 2021). "However, in the chronic lymphocytic leukemia cell model, PTPN1 could disrupt the degradation of Bcr‐Abl protein mediated by synthetic steroidal glycoside SBF‐1 via the lysosome pathway, which leads to the resistance of K562 cells to imatinib." (PMID 32395869, 2020).
chronic obstructive pulmonary disease (2 papers, 2023 to 2024). A chronic and progressive lung disorder characterized by the loss of elasticity of the bronchial tree and the air sacs, destruction of the air sacs wall, thickening of the bronchial wall, and mucous accumulation in the bronchial tree. "During respiratory syncytial viral-induced exacerbation of chronic obstructive pulmonary disease, PTPN1 deficiency was shown to promote disease symptoms partly through enhancing S100A9 levels, a damage-associated molecular pattern molecule." (PMID 36672250, 2023).
epilepsy (2 papers, 2022 to 2023). A brain disorder characterized by episodes of abnormally increased neuronal discharge resulting in transient episodes of sensory or motor neurological dysfunction, or psychic dysfunction. "In contrast, ITPR1, PTPN1, SPTBN2, and WDR81 are known as cerebellar ataxia-related genes, and there is limited evidence of shared mechanisms with epilepsy." (PMID 37645600, 2023).
LEOPARD syndrome (2 papers, 2018 to 2026). "For example, RASopathies, such asNoonan syndrome, Neurofibromatosis 1 and Leopard syndrome, are a subtype ofdevelopmental diseases characterized by mutations in genes encoding for components ofthe Ras/MAPK pathway (NF1, PTPN1, SOS1, RAF1,KRAS, NRAS, SHOC2, CBL)." (PMID 29719609, 2018).
lung adenocarcinoma (2 papers, 2020 to 2022). A carcinoma that arises from the lung and is characterized by the presence of malignant glandular epithelial cells. "Superior CAPN1 and inferior PTPN1 were related to activation of c‐Met/PIK3R2 in lung adenocarcinoma." (PMID 32395869, 2020). "This study aimed to reveal the effects of CAPN1/PTPN1 on malignant phenotype and EGFR‐TKI resistance of lung adenocarcinoma (LUAD) cells." (PMID 32395869, 2020).
memory impairment (2 papers, 2020 to 2023). "Memory impairment caused by over-expression of miR-124 can be saved by the application of miR-124 inhibitors or blocking the binding of miR-124 to PTPN1." (PMID 36961552, 2023). "Further analysis showed that over-expressed miR-124 could target for down-regulating the PTPN1, and lead to learning and memory impairment in AD model." (PMID 36961552, 2023).
pancreatic ductal adenocarcinoma (2 papers, 2021 to 2022). An infiltrating adenocarcinoma that arises from the epithelial cells of the pancreas. "In the Grutzmann dataset, compared to normal tissue, PTPN1 was overexpressed in pancreatic ductal adenocarcinoma epithelia (fold change = 1.542)." (PMID 35154122, 2022).
serous carcinoma (2 papers, 2022 to 2024). "PTPN1 was associated with multiple active ingredients of SMB in survival analysis; studies had shown that the overexpression of PTPN1 in high-grade serous carcinoma might be a marker of better response to chemotherapy." (PMID 36483919, 2022).
auditory neuropathy (1 paper, 2021). A hearing disorder characterized by impaired transmission of signals through the auditory nerve, resulting in mild to severe hearing loss and poor speech perception. "Similarly, protein tyrosine phosphatase non-receptor type 1 (PTPN11) c.1001T>A was prioritized by EVIDENCE, but this was incompatible to the phenotype of auditory neuropathy spectrum disorder (ANSD) in SB422-823." (PMID 34593925, 2021).
dilated cardiomyopathy (1 paper, 2021). Cardiomyopathy which is characterized by dilation and contractile dysfunction of the left and right ventricles. "LPIN1, PPP1R3C, PTPN1, CREM, and NR0B2 were identified as the main effectors in metabolism dysregulation in the remote zone and were found differentially expressed also in the myocardium of patients with ischemic and/or dilated cardiomyopathy." (PMID 34722683, 2021).
Duchenne muscular dystrophy (1 paper, 2025). Duchenne muscular dystrophy (DMD) is a neuromuscular disease characterized by rapidly progressive muscle weakness and wasting due to degeneration of skeletal, smooth and cardiac muscle. "Our study identifies PTPN1/2 as potential therapeutic targets for Duchenne muscular dystrophy and suggests the use of PTPN1/2 inhibitors to enhance the myogenic function of DMD muscle stem cells." (PMID 39477543, 2025).
HCMV infection (1 paper, 2022). "During HCMV infection, we find PTPN1, which deactivates EGFR at ER-endosome MCSs60, increasing in sync with EGFR downregulation." (PMID 35953480, 2022).
nephritis (1 paper, 2008). Inflammation of renal tissue. "Increased levels of transcripts for pathway members including JAK3, STAT3, SOCS3, PTPN1, CDKN1A, RRAS and MAPK1 were observed in nephritis." (PMID 18980674, 2008).
oral cancer (1 paper, 2020). "PTPN1 has been reported to be increased in canine oral cancer tissues by MALDI-TOF MS plus LC-MS/MS." (PMID 32928212, 2020).
Salmonella Infections (1 paper, 2021). Infections with bacteria of the genus SALMONELLA. "Some of them, such as tyrosine-protein phosphatase non-receptor type 1 (PTPN1), serum amyloid A-1 protein (SAA1) and chloride intracellular channel protein 1 (CLIC1), although previously reported in Salmonella infections, we have for the first time clearly associated them with SPI-2 effectors." (PMID 34461813, 2021).